CD4 (CD4 molecule)
Diseases named in the same sentence as CD4 in open-access papers (continued):
Sharing a sentence is not in itself a finding about the gene and the disease.
tumor (continued). "To test this, we depleted two known key anti-tumour immune effector cell types, CD4 and CD8 T lymphocytes, during vaccination and compared the overall survival of each group." (PMID 25186961, 2014). "To further confirm that cAMP-induced PKA-CREB pathway involves T-cell senescence, we found that treatment with the inhibitors 7-ddA and H89 dramatically decreased phosphorylation of CREB in CD4+ T cells co-cultured with tumor cells." (PMID 25231413, 2014). "The importance of CD4+ help has also been demonstrated for the recruitment, proliferation, and effector function of CTLs in the tumor microenvironment and studies demonstrated increased tumor growth after CD4 depletion." (PMID 25119341, 2014). "The CD4+ T-cells would have provided costimulation to cytotoxic T-cells, which are otherwise unable to clear the progressor tumor." (PMID 24949488, 2014). "The subsequent FACS (fluorescence-activated cell sorting, flow cytometry) analysis of splenocyte and tumor cell suspensions revealed a decrease in the CD4+ lymphocyte accumulation in the spleen and tumor." (PMID 24608924, 2014). "Studies on B cell-deficient μMT mice showed that B cell deficiency enhanced CD4+ T cell priming and helped for CD8+ T cell-mediated tumor immunity." (PMID 24991577, 2014). "CD4 T cells in the tumor comprised of cell populations with both positive and negative effects on tumor immunity." (PMID 25303284, 2014). "It was shown that when T cells from tumor-immunized donors were purified prior to adoptive transfer, Lyt1+ 2− (CD4+) T cells had a superior ability to cure FBL-3 erythroleukemic tumors compared to Lyt1− 2+ (CD8+) T cells." (PMID 24782871, 2014). "We observed that TLR8 ligands Poly-G3 and ssRNA40, but not ligands for other TLRs, markedly reversed the senescence induction in naïve CD4+ T cells mediated by the three tumor cell lines." (PMID 25231413, 2014). "We have recently demonstrated that, in OSCC, tumor nests are infiltrated by distinct subsets of CD4+FOXP3+ regulatory T cells." (PMID 24465587, 2014). "It is therefore conceivable that the low CD73 expression prevented the generation of an adenosine-mediated immunosuppressive environment involving the activation, clonal expansion and homing of tumor-specific CD4+ T helper and CD8+ cytotoxic T cells." (PMID 25465225, 2014). "Within the TUMIC, CD8+ T cells are conditioned to become CD8+FOXP3+ T regulatory cells with similar immuno-suppressive activities to that of CD4+ Tregs, adding more complexity to mechanisms by which the tumor polarization switch impairs immune responses." (PMID 25072019, 2014). "Antigen-presenting cells are thus attracted to the site of the tumor, capture tumor cell debris and present tumor antigens to CD4+ T cells through MHC class II." (PMID 24830315, 2014). "We chose this cytokine because of its role in anti-tumor immune responses being associated with both CD8 and CD4 T-cell responses, and essential for priming long-lived memory CD8+ T-cells." (PMID 25646096, 2014). "In a pilot study conducted in 15 patients treated with anti-CTLA-4 Tremelimumab, the clinical response was also associated with an increase in tumor infiltration by CD8+ TIL and a variable association with CD4+ TIL." (PMID 24741578, 2014). "CD45RA and CCR7 expression patterns indicated that both LAP+ and LAP− subsets of Foxp3+CD4+ T cells mostly had an effector/memory phenotype in peripheral blood as well as in tumor sites of CRC patients." (PMID 25268580, 2014). "It remains controversial which source of CD4+CD25-CD69+ T cells should be selected as the target for tumor immunity." (PMID 24984576, 2014). "Sustained CD8 T cell activation was observed in CD4 depleted groups, coinciding with tumor regression (days 22–35) and ultimately long term survival." (PMID 25186961, 2014). "Our results also suggested that tumor-activated γδ T cells directly lyse the target tumor cells and trigger the activation and functioning of CD4+ and CD8+ T cells." (PMID 24741609, 2014).
tumor (continued). "Do CD4+ T cell-mediated immune responses against MHC IINEG tumor cells convey bystander killing of tumor cells that have lost expression of antigen?" (PMID 24782871, 2014). "Our previous study demonstrated that CD4+CD25+ Treg cells isolated from tumor patients inhibited the proliferation of autologous effector CD4+ T cells." (PMID 24741609, 2014). "Though tumor-specific CD4+ Th cells are necessary for generation of potent antitumor immunity, there still are little known about fate of these Th cells during a lymphoma progression in brain." (PMID 24693228, 2014). "Effectors of adaptive immunity in the tumor microenvironment include CD4+ and CD8+ T cells, natural killer T (NKT) cells, dendritic cells, and infrequent B cells 16,31." (PMID 24711204, 2014). "Complete tumor eradication was observed when vaccination and surgery were performed in CD4 T cell depleted animals." (PMID 25186961, 2014). "In a humanized mouse model implanted with human breast carcinoma, Th2 cytokine expression was detected in both cancer cells and tumor-promoting CD4+ T cells within the tumor microenvironment." (PMID 24672527, 2014). "In tumor bearing mice depleted of CD4+ or CD8+ cells, the immunotherapeutic effects of miR-124 was ablated." (PMID 25594054, 2014). "The expression of HLA-G on blasts and the analysis of DC-10 and HLA-G+ CD4+ Tregs can be used to evaluate the effectiveness of anti-tumor therapies." (PMID 24741612, 2014). "Vaccine therapy aims to break immune tolerance of tumors by exposing antigen presenting cells (APCs) to immunogenic tumor peptides in the hopes of activating a broad lymphocytic immune response involving both CD4+ and CD8+ T-cells." (PMID 25268164, 2014). "The exception to this pattern is that CD4 is over-expressed (51st and 61st quantiles in tumor and cell line samples respectively)." (PMID 25380171, 2014). "We identified a small fraction of IL-17 producing CD4+ T cells in the tumor infiltrate and these comprised a significantly higher proportion of CD4+ T cells in tumor than in blood (p = 0.0008)." (PMID 24794217, 2014). "Here they demonstrated a significant reduction in the number of IFN-γ-positive NK, CD8+, and CD4+ cells within the tumours as well as tumour-draining lymph nodes." (PMID 25110397, 2014). "By this criteria, the induction of tumor lysate-reactive CD4+ T cell responses were detected in patients #1802, #1803, #1814 and #1823; patients #1802, #1812, #1814 and #1823 had tumor-reactive CD8+ T cell responses." (PMID 25694811, 2014). "Of several EBV-specific CD4+ T-cell clones tested, those directed against virion antigens proved most tumor-protective." (PMID 24853673, 2014). "Autologous tumor lysate-loaded DCs in combination with sunitinib induced both CD4+ and CD8+ T cell responses in mRCC patients." (PMID 25694811, 2014). "CD4+ regulatory T cells (Treg) and IL-17 producing T helper cells were significantly more prevalent in tumor than in blood." (PMID 24794217, 2014). "We investigated the Treg role in the PDA microenvironment by correlating the proportions of Tregs and CD4+ T cells or CD8+ T cells in the tumor tissues of PDA patients." (PMID 24637664, 2014). "Mice depleted of CD8+ cells had larger tumor volume and significantly poorer survival compared to mice depleted of CD4+ or NK1.1+ cells." (PMID 24664420, 2014). "After implantation to the partially resected tumor, the gradient of local CCL21 that resulted from its sustained and localized release led to the recruitment of CD4+ T cells and CD11c+ DCs into the tumor, while tumor infiltrating Treg cells were decreased." (PMID 24810425, 2014). "Based on our experience and on the results of many groups described in this review, we believe that a crucial and hierarchically predominant step is constituted by the efficacy of MHC class II-restricted tumor antigen presentation to CD4+ TH cells." (PMID 24600588, 2014).
tumor (continued). "A strategy to enhance the cross-presentation of the tumor antigen following chemotherapy is to promote CD4+ T helper cell immune responses." (PMID 25531529, 2014). "In the following decades, experimental evidence supporting the anti-tumor properties of tumor-specific CD4+ T cells alone has accumulated." (PMID 24782871, 2014). "In contrast, our results suggest the CD4+ T cells to be critical effectors in this MAGEA3-transfected tumor model." (PMID 24830315, 2014). "MDSC present in the tumour microenvironment have the capacity to suppress the cytotoxic effects of NK cells and the adaptive immune response mediated by CD4+ and CD8+ T cells, strongly inhibiting the anti-tumour effects of these cells." (PMID 24162378, 2014). "Dendritic cells (DCs) are the most potent professional antigen-presenting cells of the immune system, uniquely capable of stimulating tumor-specific CD4+ and CD8+ T cell immune responses leading to CTL tumor infiltration and tumor regression." (PMID 24690994, 2014). "An accumulation of CD8+ T cells, including tumor- and herpes simplex virus type-1-specific populations, and a decrease in the number of CD4+ Foxp3+ T regulatory cells were seen in both HF10- and DTA-1-treated tumors." (PMID 25105508, 2014). "In these experiments, 2- and 12-month-old mice received ovalbumin-specific CD4 T cells (2 or 12 months old) and were then challenged with a tumor cell line that expressed the surrogate antigen OVA." (PMID 24682539, 2014). "Direct cell–cell contact has also been described as a mechanism of decreasing IL-12 production, for instance by tumor-derived CD4+CD25+ T regulatory (Treg) lymphocytes via CTLA-4-mediated signaling or by CD200–CD200R interactions." (PMID 24514955, 2014). "Plasmacytoid DCs and cross-presenting CD4-CD8α+ DCs play key roles in anti-viral and anti-tumour immunity." (PMID 25089147, 2014). "As expected, the anti-CD25 mAb-treatment group significantly depleted the CD4+CD25+FoxP3+ cell population in both the tumor and spleen." (PMID 25034887, 2014). "Among the different subpopulations, Type 1 CD4+ T cells (Th1) facilitate tumor rejection by assisting in the CTL response." (PMID 25268644, 2014). "Enhancement in the tumour antigen-specific activation and proliferation of CD4+ and CD8+ T cells was observed." (PMID 28324460, 2014). "To test if TOX protein can be detected in the CD4+ T cells of MF lesions, we performed immunofluorescence (IF) staining on patch, plaque, and tumor MF biopsies, using benign chronic dermatitis (CD) lesions as the controls." (PMID 24947046, 2014). "After extensive washes, these pretreated tumor cells were co-cultured with anti-CD3 preactivated CD4+ T cells, and their capacity to induce T-cell senescence determined." (PMID 25231413, 2014). "The percentage of both tumor-infiltrating CD4+ and CD8+ T cells was dramatically decreased in AZD1480 treated mice compared to vehicle treated animals." (PMID 25149535, 2014). "The helper function of tumor-reactive CD4+ T cells improves the efficacy of tumor-reactive CD8+ T cells." (PMID 24782871, 2014). "The requirement for CD4 T cell depletion suggests a role for regulatory T cells in limiting vaccine induced anti-tumour immunity." (PMID 25186961, 2014). "Since virion antigen-specific CD4+ T cells efficiently recognize LCL in vitro, these results implicated CD4+ T cells specific for structural antigens of the virus as particularly tumor-protective." (PMID 24853673, 2014). "A further element of remodeling of the tumor microenvironment consisted in the modification of the number, but not the function, of regulatory Tregs with suppressive characteristics on CD4+ TH cells." (PMID 24600588, 2014). "Second, CD4+ T cells were pre-primed cells obtained after immunization, making it impossible to study naïve CD4+ T cells in primary anti-tumor responses." (PMID 24782871, 2014).
tumor (continued). "This importance of the presence of infiltrating CD4+ lymphocytes for the therapeutic effect of IFN-α shows that one important anti-tumor effect of IFN-α is to enhance immune reactivity toward the tumor." (PMID 24516470, 2014). "We also found that infiltrating lymphocytes from both tumor types had a higher CD8/CD4 T cell ratio compared to PBL." (PMID 25436113, 2014). "In note, they found that: H-2k H-Y+ tumor cells were rejected by I–Ab-restricted, H–Y-specific CD4+ T cells in an immunodeficient H-2b mouse." (PMID 24782871, 2014). "Depending on the polarizing signals in the tumor microenvironment the different CD4+ T cell subsets can promote or suppress a defensive host response to cancer." (PMID 24904823, 2014). "We have demonstrated that human TLR8 signaling directly reversed the suppressive functions of naturally occurring CD4+ CD25+ Treg cells as well as tumor-derived CD4+, CD8+, and γδ Treg cells." (PMID 25231413, 2014). "Such memory cells were verified by the fact that CD4+ cell depletion in vivo almost completely inhibited the anti-tumor effect, which was similar to CD8a+ or dual CD4+/CD8a+ cell depletion." (PMID 25013909, 2014). "More interestingly, it has been described that CD4+CD25+FOXP3+ Treg cells were highly enriched with TIL (tumor infiltrating lymphocytes) in advanced-stage HCC-patients." (PMID 25525301, 2014). "We examined the infiltration of CD4+/CD8a+ T cells into tumor tissues after administration of SART3/CD40L+GM-CSF gene-loaded polyplex micelles by immunohistochemical analysis." (PMID 25013909, 2014). "In the following sections, we discuss mechanism of CD4+ T cell-mediated direct killing of MHC IIPOS tumor cells and indirect killing of MHC IINEG tumor cells." (PMID 24782871, 2014). "This is consistent with our findings indicating that exosomes alter the phosphorylation of STAT proteins in tumor-induced CD4+ T cells to affect T-cell differentiation and that hsa-miR-20a-5p was over-expressed in NPC exosomes." (PMID 24978137, 2014). "Ipilimumab induced increased tumor infiltration by fully activated (CD69+) CD3+/CD4+ and CD3+/CD8+ T cells with evidence of induction/potentiation of memory T cells (CD45RO+)." (PMID 24498358, 2014). "Such shift from TH1 to TH2 polarization of CD4+ lymphocytes renders the tumor-specific cytotoxic CD8+ inactive." (PMID 25452935, 2014). "Knockdown of TLR8, MyD88, and IRAK4 in tumor cells significantly blocked the Poly-G3-mediated reversal of tumor-induced CD4+ T-cell senescence." (PMID 25231413, 2014). "γδ T cells have dual role of stimulating both γδ T cell-directed anti-tumor activity and antigen-specific CD4 and CD8 αβ T cell responses." (PMID 25426120, 2014). "CD3+CD4+CD25+CD127low T cells made up 15.5% of CD4+-T cells in tumor samples compared to 7.8% and 5.0% of PBMCs of CRC patients or healthy controls respectively (p<0, 005)." (PMID 25026291, 2014). "The role of TNFR2/p75 in tumor biology was further substantiated by increased accumulation of CD4+ CD25+ FoxP3+ T regulatory cells (Tregs) that express TNFR2+ but not TNFR− Tregs in the LLC tumor model." (PMID 24664144, 2014). "Cell depleting experiments showed that tumor protection wasdependent on the CD4+ and CD8+ T cells as removal ofCD4+ or CD8+ T cells abrogated the antitumor effectconferred by anti-PD-1/GITR mAb treatment." (PMID 24502656, 2014). "GITR-specific agonistic mAbs or recombinant GITR ligand (GITRL) fusionproteins have been shown to induce tumor regression in vivo through theactivation of CD4+ T cells, CD8+ T cells and NK cells in severaltumor models." (PMID 24502656, 2014). "Provocatively, CD4+ helper T cells were found to be the key immune effector required for oncogene inactivation-induced tumor regression in the conditional MYC-driven T-ALL mouse model." (PMID 25089198, 2014).
tumor (continued). "IL-10 has been shown to contribute in tumor derived immune suppression by suppressing CD4 T cells and inducing myeloid derived suppressor cells." (PMID 25008236, 2014). "However, in the literature, a protective anti-tumor CD8 immunity is associated with the CD4 T cell help and thus the requirement of CD4 T cell helps to induce the CD8 T cell response to tumors that could be substituted by the high immunogenicity and frequency of MuTuDC lines." (PMID 25101081, 2014). "The ratio of CD8/ CD4+ cells in transgenic mice increased from 1.17 to 1.92 after tumor injection, while it only slightly increased from 0.88 to 0.99 in wild type controls." (PMID 25594054, 2014). "This implicates regulation of the balance between CD4+CD25+Foxp3+Treg and CD4+IL-17+ Th17 as a new strategy to reverse tumor progression." (PMID 24949077, 2014). "HCV-core has also been shown by us and others to induce suppression when expressed in the CD4+ tumor T cell line Jurkat the NK cell line YTS, or when added to CD4+ T cell cultures." (PMID 24465502, 2014). "The positive prognostic association of high CD4 and CD8 T cell infiltration within a tumour implies a clinically relevant anti-tumour immune response." (PMID 25075215, 2014). "In conclusion, our data demonstrate that the frequency of CD4+CD25+Foxp3+ Tregs is significantly increased in PDA tissue and that these cells inhibit tumor-associated antigen-specific CD8+ T cells." (PMID 24637664, 2014). "Conversely, CD4 depletion enhanced CD8 T cell activation resulting in complete tumor regression in 70% of mice treated with combined surgery and vaccination therapy." (PMID 25186961, 2014). "Increased tumor infiltration with transferred Tag-specific CD4+ T cells was also observed in irradiated mice." (PMID 24434638, 2014). "As expected, increased cAMP levels in the recovered CD4+ T cells were also observed in 586mel tumor-bearing mice." (PMID 25231413, 2014). "For both MHCIIPOS and MHCIINEG tumors, presentation of tumor-specific antigen by host antigen-presenting cells (APCs) appears to be required for CD4+ T cell priming." (PMID 24782871, 2014). "In the tumor tissue, elevated numbers of Tregs as well as subpopulations of CD4+ and CD8+ T cells have been observed by several authors." (PMID 24864233, 2014). "The suppressive activities of the senescent T cells induced by different types of tumor cells on the proliferation of responding CD4+ T cells were evaluated." (PMID 25231413, 2014). "Our results show that the combination therapy inhibited tumor growth at the contralateral as well as the injected tumor sites by promoting the accumulation of tumor-specific CD8+ T cells followed by DTA-1-mediated depletion of CD4+ Foxp3+ Treg cells." (PMID 25105508, 2014). "Examination of anti-IL-1α treated tumors upon necropsy revealed an increase in tumor infiltrating CD4+ and CD8+ T cells and a decrease in the populations of both malignant LGLs and neutrophils." (PMID 24416335, 2014). "More surprisingly, CD4+ T cells can indirectly eliminate tumor cells that lack MHC class II expression." (PMID 24782871, 2014). "Immunohistochemical analysis at the tumor rejection sites revealed enormous infiltrations of CD8+ T lymphocytes as well as CD4+ T lymphocytes and CD11b+ monocytes." (PMID 25051201, 2014). "With regard to the expression of the earlier activation marker CD69, we found an increase in the percentage of CD69+CD4+ T cells in the spleen following the combined treatment, and a tendency to a reduction of the cell percentage in the tumor." (PMID 24608924, 2014). "TGF-β and IL-6 induce differentiation of CD4+ T cells into CD4+IL-17+ Th17 cells, which secrete IL-17 and IL-6 involved in inflammation and tumor development." (PMID 24949077, 2014). "CD4+CD25+Foxp3+ T cells were increasing with tumor development; however, values found in the LN from KO groups were significantly higher as compared with WT mice." (PMID 25268644, 2014).